CXCR4 (C-X-C motif chemokine receptor 4)
Diseases named in the same sentence as CXCR4 in open-access papers (continued):
Sharing a sentence is not in itself a finding about the gene and the disease.
tumor (continued). "High levels of TAMs were observed in tumors with increased expression of stromal-cell-derived factor 1 alpha (SDF-1α), CXCL12, C-X-C motif chemokine receptor 4 (CXCR4) and VEGF in mouse tumor models." (PMID 34149730, 2021). "CXCR4, the receptor of stromal cell-derived factor (SDF)-1α, can be induced to overexpress on invading tumor, macrophages/microglia and GSCs in hypoxia-niche, and is a therapeutic target for patients suffering from GBM." (PMID 34368156, 2021). "To address this question, we used IHC staining to analyze the expression of HOXB5, CXCR4 and ITGB3 in primary tumor tissues and adjacent non-tumor tissues from two independent CRC patient cohorts." (PMID 33456563, 2021). "Studies have shown that some neutralizing antibodies or inhibitors targeting chemokine systems (CXCR4, CXCR2, and CCL2) and tumor-derived factors (CSF1, GM-CSF, and IL-6) can inhibit the expansion or recruitment of MDSC." (PMID 34447750, 2021). "PLA was performed using unconjugated anti-CXCR4 and anti-CCR7 antibodies, together with an Alexa Fluor® 488 anti-EpCAM antibody to distinguish epithelial tumour areas from tumour stroma for subsequent quantitation." (PMID 34685420, 2021). "Blockade of CXCR4, the receptor of CXCL12, enhanced macrophage and CD8 TIL infiltration and reduced tumor growth and subsequent metastasis." (PMID 33988305, 2021). "Tumor and stromal cells produce CXCL12, which is the ligand of chemokine receptor CXCR4, expressed by pDCs." (PMID 34575965, 2021). "In this study, also the compound AMD3100, an antagonist of the CXCR4 (chemokine receptor type 4) axis, was able to inhibit CAFs-induced CRC cells invasion and to completely prevent the effects related to tumor progression." (PMID 33498521, 2021). "For example, PRX177561, another CXCR4 antagonist, has been tested in GBM both in vivo and in vitro, and studies have shown that it reduces tumor growth, blocks the polarization switch of macrophages from M1 to M2 and reduces GSCs stem-like features." (PMID 33530455, 2021). "In the case of RCC-PDC2, the original patient tumor contained a tissue portion of ccRCC cells with eosinophilic cytoplasm and high NRN1/CXCR4 IHC staining, which feature was recapitulated in the established PDC spheroid culture and its PDCX tumor." (PMID 34804954, 2021). "Despite disappointing results in trials utilizing anti-CXCR4 strategies, the CXCR4/SDF-1 axis warrants further study to define its role in tumor progression, recurrence, and metastasis, as well as elucidate the impact on the tumor microenvironment." (PMID 33507926, 2021). "CXCL12, also known as stromal cell-derived factor-1α, binds to its receptor CXCR4 and activates the CXCR4/CXCL12 axis; this leads to tumor proliferation, vascularization, and metastasis." (PMID 34885013, 2021). "Immunofluorescence co-staining confirmed that a low number of CXCR4+ MDSCs were present in U251-BATF2 tumours, and very few CXCR7+ MDSCs were observed in both U251-Ctrl and U251-BATF2 tumours." (PMID 33452462, 2021). "Cells from the primary tumor and metastasis display differences in the levels of the cognate receptors, as the H295R cells express both receptors, while the MUC-1 ones only CXCR4 at a significantly higher level than in the other cell model." (PMID 34834449, 2021). "Since CXCR4-expressing tumor cells can migrate to normal tissue expressing SDF-1, the SDF-1/CXCR4 pathway has been shown to play a crucial role in mediating tumor metastasis." (PMID 33946266, 2021). "Taken together, our results confirm the central role of HIF-1α in the interactions between the tumor microenvironment and CLL cells, also elucidating the interplay with the CXCL12/CXCR4 axis." (PMID 34207596, 2021). "The expression of miR-9 directly targeted CXCR4 signaling in GBM; it functioned as a tumor suppressor by inhibiting the migratory capacity of GBM cells in vitro." (PMID 34203660, 2021).
tumor (continued). "We further investigated the mechanisms of radiation resistance by measuring the expression levels of certain proteins involved in tumor proliferation- and metastasis-related pathways (IL-6/STAT3, SDF-1/CXCR4, and PI3K/AKT/mTOR)." (PMID 34539883, 2021). "It was demonstrated that the combination of CXCL12 with CXCR4 and CXCR7 on tumor cells leads to antiapoptotic signals upregulated by Bcl‐2 and survivin, and affects the progression of gastrointestinal tumors." (PMID 33979042, 2021). "The IL-33-enhanced-CXCR4 regulatory circuit involves SDF1/CXCR4 signaling activation and modulates tumor behavior." (PMID 34298657, 2021). "CXCR4 is selectively expressed on a fraction of tumor endothelial cells in HCC tissues, and high levels of CXCR4 tend to develop a sinusoidal vasculature in tumors, which can be used as a novel vascular marker for vessel sprouting in HCC tissues." (PMID 34386499, 2021). "The CXC chemokine receptor type 4 (CXCR4) receptor and its ligand, CXCL12, are overexpressed in various cancers and mediate tumor progression and hypoxia-mediated resistance to cancer therapy." (PMID 33753481, 2021). "The expressions of CXCR4, FGF-2 and ERK2 in the IR/Contra-tumor group were significantly higher than those in the Sham-IR/Tumor group." (PMID 34764346, 2021). "They promote angiogenesis and tumor growth through the secretion of SDF-1 (stromal-cell derived factor 1), which binds to their receptor, CXCR4." (PMID 33472580, 2021). "The effects of the L1CAM, CXCR4 and NODAL on tumor growth, proliferation, migration, invasion, colony-formation ability, metastasis and chemoresistance were investigated both in vitro and in vivo." (PMID 33897875, 2021). "By comparing the gene expression profiles of orthotopic and subcutaneous PCa tumours, we selected five widely used CSC markers (ALDH, CD44, CXCR4, α2β1 and CD24) to sort candidate PCSCs from orthotopic PCa tumours." (PMID 34247196, 2021). "In typical CLL cases, the tumor B cell clone exhibits an abnormal expression of markers like CD5, CXCR4, and ZAP-70, that are used to stratify the disease in conjunction with the mutational status of the BCR reflecting different cell of origin." (PMID 34956214, 2021). "Given the increased expression of XBP1, CXCR4, and CD44 during ERS/UPR activation under hypoxic condition in DLBCLs, we further investigated possible contribution of this pathway to the tumor APVT growth pattern." (PMID 34093792, 2021). "FL tumor cells expressing CXCR4, CXCR5 and CCR7 home in both BM and LN, and the interaction of CXCR12 expressed on BM stromal cells of the lymph node/BM with CXCR4 expressed by tumor cells, has been found to play a critical role in this context." (PMID 34395425, 2021). "In the present study, it was found that the expressions of CXCR4 and LCK in the tumor tissue of the Hespintor treatment group were significantly higher than those of the solvent control group, which appeared to be contrary to the general theory." (PMID 33391431, 2021). "MAIT cells from responders express higher level of CXCR4 and produce more granzyme B. In silico analysis support MAIT presence in the tumor microenvironment." (PMID 33723257, 2021). "Further, as a possible mechanism of tumor-to-tumor metastasis, the involvement of both C-X-C motif chemokine ligand 12/stromal cell-derived factor-1 (CXCL12/SDF-1) and C-X-C motif chemokine receptor 4 (CXCR4) is examined." (PMID 34187383, 2021). "Knocking down XBP1, CXCR4, and CD44 by siRNA technology altered the interplay between tumor cells and HBMECs." (PMID 34093792, 2021). "Various promoter candidates have been applied to design tumor-specific promoter-driven OVs, including nestin, survivin, cyclooxygenase-2 (COX-2), C-X-C chemokine receptor type 4 (CXCR4), hypoxia inducible factor-1 (HIF-1) and telomerase." (PMID 33557101, 2021).
tumor (continued). "RT-PCR analysis of CXCR4, FGF-2, VEGF-A, EGFR, and ERK2 (MAPK1) revealed significantly higher expression of three genes (i.e., CXCR4, FGF-2, and ERK2) in IR/Ipsi-tumor and IR/Contra-tumor groups compared to the control groups." (PMID 34764346, 2021). "Among these factors regulating the trafficking of tumor cells, CXCL12 seems to be especially relevant, as metastatic cells express its major receptor, CXCR4." (PMID 34112253, 2021). "Simultaneous depletion of TAMs with zoledronic acid and treatment with sorafenib inhibited primary tumor growth and lung metastasis in an orthotopic HCC model through the reduction of the CXCR4+ vascular density." (PMID 34209679, 2021). "CXCR4 surface expression is regulated by its ligand, thus explaining the decrease in CXCR4 expression on tissue tumor B cells, while recirculating CLL B cells express high levels of CXCR4." (PMID 34956214, 2021). "CXCR4 selectively binds with stromal cell-derived factor 1 (SDF1), also known as C-X-C family chemokine ligand 12 (CXCL12) (CXCL12/SDF-1), which induced tumor proliferation and metastasis." (PMID 34220311, 2021). "The specific binding of SDF-1 and CXCR4 form the SDF-1/CXCR4 biological axis, which is a key signal axis that mediates the interaction between tumor cells and stromal cells, and is highly related to cell adhesion, migration and invasion." (PMID 34733839, 2021). "Our findings suggest a pivotal role of let-7f in the cytokine/chemokine-mediated tumor tropism of hMSCs involving its positive regulation of MMP-9 and CXCR4." (PMID 34016957, 2021). "Currently, the promotion of stem cells migration to tumor is mainly achieved through the CXCR4/ SDF-1α axis, and the expression of CXCR4 in stem cells can be further enhanced by hypoxia induction." (PMID 34069607, 2021). "We have shown that inhibition of CXCR4 releases the matrix‐retained, now active CD8 TIL (as Ifnγ and Gzmb expression was elevated) to infiltrate the tumor tissue thus increasing tumor cell death and reducing tumor growth and subsequently metastasis." (PMID 33988305, 2021). "CXCL12/CXCR4 axis promotes migration and survival of MDSCs in osteosarcoma inhibiting cytotoxic T cell (CTL) expansion and thus controlling tumor growth." (PMID 33937018, 2021). "The maintenance of tumour vasculature appears to involve CXCR4 activity, with CXCR4 antagonists reducing GSC production of VEGF, tumour cells’ ability to mimic vascular structures and the number of CD31+ or VEGF+ cells intratumourally." (PMID 33803414, 2021). "The metastatic potential was consistently reduced in lung and tumor when hMSCs were pre-treated with stromal cell derived factor-1 (SDF-1) blocker, AMD3100, suggesting that the SDF-1/CXCR4 axis was one of the prime movers in the metastatic process." (PMID 33838662, 2021). "The expression of XBP1s, CXCR4, and CD44 in tumor biopsy samples was downregulated in siRNA lentivirus-transfected xenografts." (PMID 34093792, 2021). "ShRNA-mediated silencing of ANXA1 suppresses nuclear factor (NF)-kB activity, which results in the direct inhibition of CXCR4 and matrix metalloproteinase (MMP) expression, impeding tumor cell invasion." (PMID 34200100, 2021). "Here, we reported that MK3 expression was positively correlated with the majority of chemokines and chemokine receptors, such as CCL, CXCL12, CCR, CXCR2, CXCR4, and CX3CR1, which play pro-tumor roles." (PMID 34938665, 2021). "During tumor development and in cancer therapy, HMGB1 is released and plays multiple roles through binding receptors, including RAGE, TRL2/4, TIM3 and CXCR4." (PMID 34257571, 2021). "Conversely, purified TNF-α treatment resulted in enhanced NF-κB activity and CXCR-4 expression, which further suggests that TNF-α is an important mediator of tumor-infiltrating pDC in the promotion of tumor growth and metastasis." (PMID 33854604, 2021).
tumor (continued). "CCL-2 and CXCL-12 can aid in angiogenesis and impede endothelial cells' apoptosis through straight receptor (CXCR-4 and CCR-2) binding on tumour vessels or obliquely propping up drafting in leukocytes." (PMID 34336101, 2021). "Targeting CXCR4 with AMD3100 also prevents the polarization toward an immunosuppressive microenvironment after sorafenib treatment, suppresses HCC tumor growth, reduces metastasis and improves survival." (PMID 34386499, 2021). "The differential quantitative expression of the CXCR4/CXCR7 receptors and their ligand CXCL12 was evident between the tumor samples from a pilot cohort of n = 22 ACC patients and n = 26 normal adrenals." (PMID 34834449, 2021). "Of the various chemokine signaling networks, the C-X-C Motif Chemokine Ligand 12 (CXCL12)/CXCR4 axis is recognized as a prominent moderator of the supportive tumor microenvironment (TME) and tumor-stroma interactions." (PMID 34453639, 2021). "The clinical course of BPDCN shows progressive systemic expansion, partially attributed to the local production of chemokine ligands of CKR expressed by the tumor cells (CXCR3, CXCR4, CCR6, CCR7)." (PMID 34778050, 2021). "It was correlated with high-grade tumours and poor overall survival and involved in ALDH+CD44+CXCR4+CD24+-cell-rendered castration resistance." (PMID 34247196, 2021). "BL-8040 (motixafortide) is a CXCR4 antagonist, and a phase 2 study shows that BL-8040 increases CD8+ T cell tumor infiltration, decreases myeloid-derived suppressor cells and circulating regulatory T cells (COMBAT trial) (NCT02826486)." (PMID 33572223, 2021). "We previously established a predictive model incorporating the tumor properties of vascular invasion and TNM stage, and CXCR4, CTGF, and IL-11 proteins to predict bone metastasis in HCC." (PMID 33588789, 2021). "CXCR4 plays various roles in HCC progression, including promoting angiogenesis, maintaining tumor growth, inducing epithelial-mesenchymal transition, promoting invasion and spread, and helping tumor cells evade immune surveillance." (PMID 33859758, 2021). "When the CXCR4 knockdown cell line, Eca109, was inoculated subcutaneously into BALB/c-nu/nu mice, the tumor mass formed at the inoculation site was significantly smaller than the control group." (PMID 33710803, 2021). "The mechanisms underpinning CXCR4-medicated malignant transformation of GPL and alteration of tumor immunity should be explored in the future." (PMID 34676245, 2021). "We found that the PBNK cells express prime chemokine receptors, such as CXCR3, CXCR4, CCR5, and CXCR6, that match chemokines produced by the studied tumor cells." (PMID 33919155, 2021). "CXCR4 is a member of the CXC chemokine receptor family, involved in regulating cancer progression by binding to unique ligands in the tumor microenvironment." (PMID 34496868, 2021). "However, the horseshoe crab derivative CXCR4 ligand T22 is one of the few tumor-homing peptides that shows high affinity for CXCR4 in a recombinant form, being also capable of promoting selective uptake of macro-molecular complexes and NPs inside CXCR4 overexpressing cells." (PMID 34208189, 2021). "In this review, we focus on the contribution of the CXCL12/CXCR4/CXCR7 axis in signaling in tumor/TME cells and we evaluate the possible combined targeting of CXCR4 and CXCR7." (PMID 33937018, 2021). "The CXCL12/CXCR4 axis can activate the MEK/ERK, PI3K/AKT, and Wnt/β-catenin pathways to promote EMT, thereby promoting tumor invasion and metastasis." (PMID 34447750, 2021). "In cancer, the CXCR4-SDF-1α axis fulfills several tumor-growth supporting functions, including stimulation of tumor proliferation and angiogenesis, promotion of tumor invasiveness." (PMID 34683912, 2021).
tumor (continued). "Tumour expression levels of αvβ3, CD31, Ki-67, and CXCR4 were further analysed for the evaluation of biological behaviours." (PMID 34121134, 2021). "The chemokine CXCL12 and its cognate receptor CXCR4, a transcriptional target of FOXC1 was shown to play central roles in cancer proliferation, angiogenesis, invasion, tumor microenvironment, as well as drug resistance induced by chemotherapy." (PMID 34540690, 2021). "It is reported that the expression levels of CX3CR1, CXCR4, CXCR5, and CCR7 in tumor tissues are significantly increased, which is able to affect the survival time of patients." (PMID 34603645, 2021). "They migrate to the tumor formation site through specific communication among cytokines and their receptors, for example, CCR3, -5, -7, and CXCR4." (PMID 34821729, 2021). "Chemokine (C-X-C motif) receptor 4 (CXCR4) and its ligand, the alpha-chemokine CXCL12, has been described to play a central role in tumor growth and progression, tumor invasiveness and metastasis." (PMID 33579381, 2021). "We developed different ACC xenograft mouse models to study the RGZ effects in vivo on tumor growth and the CXCL12/CXCR4 axis in a therapeutic and a prevention setting, comparing them with MTT." (PMID 34834449, 2021). "Up-regulation of miR-15a/16-1, regulated by CXCR4, results in the repression of BCL-2 and cyclin D1. miR-15a/16-1 increases apoptosis and reduces the proliferation and survival of tumor cells." (PMID 33718173, 2021). "Gene expression analysis of AQP1, HIF-1α, HIF-2α, CXCR4, NMYC, NCAM mRNA reveals major differences between tumors but also between different areas of the same tumor, demonstrating great inter- and intra-tumor heterogeneity." (PMID 33467498, 2021). "The CSC niche components reviewed above play a crucial role in the regulation of the CXCL12/CXCR4 axis, interacting with each other and with the CSC population to sustain the tumor." (PMID 33530455, 2021). "Neutralizing CXCR4 antibody mitigated lung metastasis promotion by MRE11 overexpression, as evidenced by decreased luminescence and tumor nodule formation." (PMID 33927349, 2021). "Meanwhile, the CXCR4 and CD44 expression was significantly upregulated in DLBCL tumor cells under hypoxic condition." (PMID 34093792, 2021). "In conclusion, CXCR4 was a novel biomarker correlated with malignant transformation of GPL and played a vital role in the control of tumor immunity." (PMID 34676245, 2021). "In this review, we will provide the latest evidence about the interactions between CSC niche-derived CXCL12 and its receptors—CXCR4 and CXCR7—present on CSC populations across different tumor entities." (PMID 33530455, 2021). "In this study, we observed the expression, interaction, and roles of CXCR4 and BIRC5 in GBM tumour samples in relation to epigenetics, stemness, and immunity." (PMID 34685742, 2021). "In conclusion, the present study demonstrated that the expression levels of CXCR4, CXCR5 and CCR7 were significantly higher in tumor tissues." (PMID 32896997, 2020). "CXCR4, a G-protein-coupled receptor, is a receptor for SDF-1α and a crucial mediator of cell migration in both leukocytes and tumor cells." (PMID 32344892, 2020). "Several studies have shown that miR-126 targets include ADAM9, LRP6, PIK3R2, CXCR4, and SLC7A5, all of which participate in the development of diverse tumor types." (PMID 32554852, 2020). "When radiotherapy or chemotherapy of solid tumors was combined with the administration of a CXCR4 antagonist such as AMD3100, a significant decrease in primary tumor volume and reduced metastatic burden was observed." (PMID 31802362, 2020). "CXCL12/CXCR4 plays an important role in the recruitment of Treg cells into the TME, and contributes to immune suppressive activities and tumor-related inflammation in HCC and malignant pleural mesothelioma." (PMID 31991604, 2020).